RN7SL328P (RNA, 7SL, cytoplasmic 328, pseudogene)
Gene: Miscellaneous RNA gene on chromosome 9 (131,725,168 to 131,725,467, reverse strand). Ensembl gene ENSG00000240853.
Homologues: Orthologues: chimpanzee Metazoa_SRP (98% identical), macaque Metazoa_SRP (87% identical). Paralogues in human: RN7SL1 (80% identical), RN7SL2 (79% identical), RN7SL709P (79% identical), RN7SL3 (78% identical), RN7SL45P (77% identical), RN7SL220P (77% identical), RN7SL333P (77% identical), RN7SL577P (77% identical), RN7SL60P (77% identical), RN7SL448P (77% identical), RN7SL597P (77% identical), RN7SL769P (77% identical), and 701 more.